WNT5B (Wnt family member 5B)
Diseases named in the same sentence as WNT5B in open-access papers (continued):
Sharing a sentence is not in itself a finding about the gene and the disease.
osteoporosis (2 papers, 2021 to 2025). A condition of reduced bone mass, with decreased cortical thickness and a decrease in the number and size of the trabeculae of cancellous bone (but normal chemical composition), resulting in increased fracture incidence. "However, several genetic studies link single nucleotide polymorphisms (SNPs) near WNT5B to osteoporosis." (PMID 34017835, 2021). "The SNP (rs2887571) at the WNT5B enhancer alters ERα binding, affecting WNT5B expression in osteoporosis." (PMID 40612684, 2025). "The effect of WNT5B on osteoporosis is still unclear due to the lack of research on WNT5B in normal bone cells." (PMID 34017835, 2021).
scleroderma (2 papers, 2023 to 2024). Scleroderma is a rare autoimmune connective tissue disorder characterized by abnormal hardening of the skin and, sometimes, other organs. "In contrast, activated sublining FLS were transcriptionally similar to ACTA2+ myofibroblasts and WNT5B+ fibroblasts in the colon as well as two populations of dermal fibroblasts expanded in scleroderma as compared to healthy skin (CCL19+APOE+CXCL12+ and SFRP2hiPRSS23+THY1+)." (PMID 37277655, 2023).
Stroke (2 papers, 2012 to 2014). Sudden impairment of blood flow to a part of the brain due to occlusion or rupture of an artery to the brain. "This phenomenon was exaggerated in aged rats by an increased expression of several new “stroke genes,” including Il13a, Rassf4, Tgfbi, and Wnt5b, in the peri-lesional cortex of aged rats only." (PMID 24672479, 2014). "However, one third of the genes were increased with suboptimal timing in aged rats, either on day 3 post-stroke (Adam17, Gpc3, Mmp14, Nid2, Tagln, Wnt5b) or on day 14 after stroke (Col4a2, Col8a1, Cthrc1, Cxcl1, Gpc3, Tgfbr2)." (PMID 23251410, 2012).
acute lymphoblastic leukemia (1 paper, 2020). Leukemia with an acute onset, characterized by the presence of lymphoblasts in the bone marrow and the peripheral blood. "Other Wnts such as Wnt4, Wnt5B, Wnt6, Wnt7B, Wnt9A, Wnt10A, Wnt14, and Wnt16 are robustly expressed in CLL B-cells and acute lymphoblastic leukemia (ALL) cells, whereas these can be scarcely detected in normal pre-B cells." (PMID 33126517, 2020).
acute myeloid leukemia (1 paper, 2021). Acute myeloid leukemia (AML) is a group of neoplasms arising from precursor cells committed to the myeloid cell-line differentiation. "WNT5B was also shown to be highly expressed in EpCAM+ cells (leukemia stem cells) in acute myeloid leukemia (AML) and to associate with the resistance of EpCAMhigh myeloid leukemia cells to cytotoxic chemotherapy." (PMID 34017835, 2021).
atypical teratoid rhabdoid tumor (1 paper, 2021). Atypical teratoid rhabdoid tumor (ATRT) is a highly malignant central nervous system (CNS) rhabdoid tumor (RT) found almost exclusively in children. "The expression of WNT5B has been shown in gliomas and atypical teratoid rhabdoid tumors (ATRT), but studies beyond gene expression have not been performed." (PMID 34017835, 2021).
bone cancer (1 paper, 2022). A primary or metastatic malignant neoplasm affecting the bone or articular cartilage. "Wnt5b and the co-receptor RYK were upregulated in the sensory dorsal root ganglia of bone-tumor-bearing mice and therefore were assumed to participate in the transduction of pain due to bone cancer." (PMID 36497192, 2022).
bone sarcoma (1 paper, 2015). A sarcoma that arises from the bone. "In contrast, among noncanonical Wnt ligands, the expression of Wnt5a, Wnt5b and Wnt16 was either decreased or lost in bone sarcoma cells; however, Wnt6, Wnt7b, and Wnt11 were remarkably increased in bone sarcoma cells." (PMID 25999350, 2015).
chronic lung disease (1 paper, 2019). According to the definitions of the American and British Thoracic Societies, including pulmonary functional tests, X-rays, and CT scans for items such as fibrosis, bronchiectasis, bullae, emphysema, nodular or lymphomatous abnormalities. "Aberrant expression of the non-canonical ligands WNT-5A and WNT-5B has been reported to contribute to inflammation, stem cell ageing, and chronic lung diseases; however, their impact on alveolar epithelial repair is unclear." (PMID 31557955, 2019).
Chronic myeloid leukemia (1 paper, 2022). "Chronic myeloid leukemia cases showed a significant upregulation of WNT5B, as a known oncogenesis gene." (PMID 35176183, 2022).
disc degeneration (1 paper, 2024). "In degenerative nucleus pulposus cells, LRP5 activates Wnt5B, which promotes apoptosis and inflammatory responses in nucleus pulposus cells by regulating the Wnt/Ca2+ signaling pathway, thereby promoting disc degeneration." (PMID 38654287, 2024). "In degenerated nucleus pulposus cells, LRP5 activate Wnt5B, which promotes nucleus pulposus cell apoptosis and inflammatory response by regulating the Wnt/Ca2+ signaling pathway, thereby promoting disc degeneration." (PMID 38654287, 2024). "Our analysis suggests that wnt5B, which is activated by LRP5, promotes apoptosis and inflammatory responses in nucleus pulposus cells by regulating the Wnt/Ca2+ signaling pathway, thereby promoting disc degeneration." (PMID 38654287, 2024).
endometrial cancer (1 paper, 2019). Primary or metastatic malignant neoplasm involving the endometrium (mucous membrane that lines the endometrial cavity). "In summary, dysregulation of O-GlcNAcylation supports EMT and cytoskeletal re-organization in endometrial cancer cells, potentially through activation of the noncanonical Wnt signaling pathway via WNT5B." (PMID 31080560, 2019).
glioma (1 paper, 2020). A benign or malignant brain and spinal cord tumor that arises from glial cells (astrocytes, oligodendrocytes, ependymal cells). "In the present study, we also revealed that increased mRNA expressions of WNT16 was associated with shorter OS in patients with glioma, while the increased mRNA expressions of WNT3 and WNT5B were associated with longer OS." (PMID 32181818, 2020). "Conversely, the increased mRNA expression levels of WNT3, WNT5B and WNT10B were correlated with better OS in patients with glioma." (PMID 32181818, 2020). "For WNT10B, in contrast with the results of WNT5B, significant lower mRNA expression of WNT10B in glioma was observed compared with NB." (PMID 32181818, 2020).
Hydrocephalus (1 paper, 2024). Hydrocephalus is an active distension of the ventricular system of the brain resulting from inadequate passage of CSF from its point of production within the cerebral ventricles to its point of absorption into the systemic circulation. "We identified rhythmically expressed genes, which have been associated with developmental processes, such as hydrocephalus-associated genes (Ccdc88c, Hydin), and several rhythmically expressed mitogens, which are likely diurnally released into CSF (Wnt5b, Angpt1-2, Ccn2)." (PMID 38802875, 2024).
Hyperglycemia (1 paper, 2020). An increased concentration of glucose in the blood. "We observed significant downregulation of Mafa, Ins1, and Ins2 mRNAs, and significant upregulation of Aldob, Slc5a10, Wnt5b, Hk1, and Tnfrsf11b mRNAs, suggesting that the molecular defect results directly from the loss of Cnot3, rather than to hyperglycemia." (PMID 32859966, 2020).
leukoplakia (1 paper, 2025). A white patch or plaque on a mucous membrane that cannot be characterized clinically or pathologically as any other disease. "Among these four Wnt ligands, mRNA levels of Wnt3a, Wnt5b and Wnt7b are upregulated in leukoplakia and early stage OSCC, suggesting that if a causality is determined between periodontitis and OSCC, these ligands may participate in initiating malignant transformation of normal oral cells." (PMID 40421179, 2025). "According to our transcriptomic analysis, significant upregulation of Wnt5b mRNA occurs during leukoplakia and early stage OSCC." (PMID 40421179, 2025).
liver cancer (1 paper, 2021). An epithelial or non-epithelial malignant neoplasm that arises from the liver. "However, it promoted liver tumorigenesis in HCC mice models via initiation of liver cancer stem cells (LCSCs) through Wnt5b‐Fzd5 mediating β‐catenin signaling." (PMID 33931972, 2021).
liver fibrosis (1 paper, 2022). "The observed up-regulation is also consistent with the previous studies linking high FZD8 levels and WNT5B to activation of noncanonical Wnt signalling during lung and liver fibrosis." (PMID 36156078, 2022).
metastatic tumors (1 paper, 2015). "WNT5A and WNT5B are ligands for and bound by FZD2 and FZD4, and this binding has been shown to drive EMT and is elevated in metastatic tumors." (PMID 26572553, 2015).
muscular disease (1 paper, 2024). Myopathy is a peripheral nervous system disease consisting of any abnormal condition or disease of the muscular tissues; commonly designates a disorder involving skeletal muscle. "Finally, our findings indicate that Wnt5b-Ror2 signaling in MPs can serve as a suitable diagnostic and therapeutic target for sarcopenia and various muscular diseases, including DMD." (PMID 39468010, 2024). "It will be of interest to examine how much extents Ror2 signaling, activated synergistically by Wnt5b and Wnt11, will contribute to the progression of muscular diseases accompanied with IMAT accumulation including DMD and sarcopenia." (PMID 39468010, 2024).
nasopharyngeal carcinoma (1 paper, 2018). A carcinoma arising from the nasopharyngeal epithelium. "Furthermore, we found that Wnt5B, SFRP1, and SFRP2 were hypermethylated in nasopharyngeal carcinoma tissues, and the hypermethylation of DKKs and DACTs in nasopharyngeal carcinoma tissues was also confirmed." (PMID 30075814, 2018).
Nephroblastoma (1 paper, 2023). An embryonal neoplasm characterized by the presence of epithelial, mesenchymal, and blastema components. "In a study to identify genes driving early events in the formation of Wilms tumours, or nephroblastomas, the gene WNT5b was identified to have upregulated expression in human Wilms tumour blastemal cells as compared to differentiated kidney glomerular cells." (PMID 37580336, 2023). "WNT5B protein expression was detected in human developing kidneys subsequent to renal vesicle formation, with expression in the nuclei of differentiated kidneys and in the cytoplasm in Wilms tumour tissue." (PMID 37580336, 2023).
oral cancer (1 paper, 2021). "Moreover, Wnt5B can induce lymphangiogenesis and EMT phenotypes in oral cancer by regulating the expression of Snail and Slug proteins." (PMID 33668218, 2021).
periodontitis (1 paper, 2025). An acute or chronic inflammatory process that affects the tissues that surround and support the teeth. "Together, it was found that Wnt ligands Wnt3, Wnt3a, Wnt5b and Wnt7b are concomitantly upregulated in periodontitis and oral carcinogenesis." (PMID 40421179, 2025). "By analyzing the GEO databases GSE223924 and GSE85195 we found that the Wnt ligands Wnt3, Wnt3a, Wnt5b and Wnt7b are transcriptionally upregulated in periodontitis and OSCC, especially during early carcinogenic phases." (PMID 40421179, 2025). "Interestingly, the transcriptional upregulation of Wnt3, Wnt3a, Wnt5b and Wnt7b in periodontitis (GSE223924) was also observed in oral carcinogenesis (GSE85195)." (PMID 40421179, 2025). "Transcriptomic Z-score analysis shows that among 19 Wnt ligands available, two canonical Wnt ligands (Wnt3 and Wnt3a) and two non-canonical Wnt ligands (Wnt5b and Wnt7b) are upregulated in periodontitis." (PMID 40421179, 2025).
pleomorphic liposarcoma (1 paper, 2008). Pleomorphic liposarcoma (PLS), the rarest subtype of liposarcoma (LS), is an aggressive, fast growing tumor located usually in the deep soft tissues of the lower and upper extremities. "This implies, similar to WNT5B, tumor suppressor function in pleomorphic liposarcoma, though the status of the remaining allele is unknown." (PMID 18784837, 2008).
pulmonary fibrosis (1 paper, 2025). Chronic progressive interstitial lung disorder characterized by the replacement of the lung tissue by connective tissue, leading to progressive dyspnea, respiratory failure, or right heart failure. "Among the identified candidate genes, the COL6A3, COL7A1, WNT5B, and MMP3 have been demonstrated to be associated with pulmonary fibrosis." (PMID 40034336, 2025).
cancer (40 papers, 2010 to 2025). A tumor composed of atypical neoplastic, often pleomorphic cells that invade other tissues. "In fact, WNT5B associated exosomes promoted cancer cell migration and proliferation in a paracrine manner." (PMID 31324218, 2019). "CRC Wnt5b-associated exosomes promote cancer cell migration and proliferation by inducing matrix metallopeptidases (MMPs)." (PMID 31402975, 2019). "Wnt5a, Wnt5b, and Fzd2 13 are crucial proteins reported to associate with cancer stemness and mobility." (PMID 27139420, 2016). "Furthermore, WNT5B, a gene identified within our scRNA-seq Trailblazers has been implicated in cancer aggressiveness in a number of cancer cell lines and tissues." (PMID 29199959, 2017). "In the "CTNNB" (or β-catenin) keyword, both WNT5B (a representative Wnt family protein) and β-catenin are well-known pathways in carcinogenesis; and elevated expression of these molecules have been associated with AR, ER, and cancer progression." (PMID 21134280, 2010). "Although WNT5B has been shown to be overexpressed and correlated with poor overall prognosis in other cancer types, nothing is known about its role in OS." (PMID 38689429, 2024). "Due to WNT5B's inhibitory effect on osteoblast differentiation and positive regulation of MSCs, as well as its overexpression in various human cancers, we investigated the role of WNT5B in OS." (PMID 38689429, 2024). "In these cancers, WNT5B has been shown to affect proliferation, differentiation, migration, invasion and tumour size." (PMID 38689429, 2024). "Concordant with our findings, those of a previous study have shown that the Wnt5b protein carried by exosomes promotes cancer cell proliferation in a paracrine manner." (PMID 37373600, 2023). "In this study, we found that the JAG1 level on PDAC organoids was increased by ductal differentiation, and JAG1 consequently increased the WNT5B and TGFb1 levels by stimulating ECs, leading to cancer cell plasticity and anti-inflammatory microenvironment." (PMID 35673567, 2022). "MMP-3 participates actively in cancer progression since it inhibits the Wnt5b favoring the activation of the canonical Wnt signaling pathway to induce cancer stem cells differentiation and expansion." (PMID 36213817, 2022). "WNT5B is upregulated in several cancer types, knowning to activate both canonical WNT/β-Catenin and non-canonical WNT signalling." (PMID 35982038, 2022). "WNT3 and WNT5B are secreted from mesenchymal-transitioned cancer cells to induce the metastatic potential of neighboring epithelial cells." (PMID 34017835, 2021). "As in many other cancer types, knockdown of WNT5B decreased OSCC cell line proliferation and migration." (PMID 34017835, 2021). "As classic signaling molecules, EV-shuttled Wnt signaling molecules, such as Wnt 11, Wnt3a, Wnt5b, and Wnt4, have been reported to be involved in cancer progression." (PMID 33234148, 2020). "Previously, EV-mediated transfer of Wnt 11, Wnt3a, Wnt5b, and Wnt4 has been described in the progression of various cancers." (PMID 33234148, 2020). "LGK-974 (also known as WNT-974, a Phase I drug for TNBC and other Wnt ligands-dependent cancers) is a Porcupine inhibitor and can inhibit Wnt5a and Wnt5b secretion effectively." (PMID 31462314, 2019). "This study employs a high-fidelity 3D culture model to reveal the reverse link between the expression levels of WNT5B in alternatively activated macrophages and cancer cells, possibly leading to T-cell exclusion." (PMID 31324218, 2019). "A recent study demonstrated that Wnt5b promotes cancer cell migration and proliferation by exosome-mediated secretion." (PMID 31462314, 2019). "In macrophages grown as co-culture with cancer cells expression of three ligands of Wnt pathway increased significantly: Wnt5b, Wnt7a and Wnt7b." (PMID 22353646, 2012). "So far, there is only one report that Wnt-5b is upregulated in cancer cell lines and little is known about the role of Wnt-5b in cancer." (PMID 21998657, 2011).
cancer (continued). "Ingenuity analysis identified a group of 7 genes (BEX1, FBLN1, FGD3, HBEGF, KLK3, KLK6, and WNT5B) related to cancer, cellular function and maintenance, cellular growth, invasion, as well as proliferation with P < 0.001-0.05." (PMID 21134280, 2010). "Therefore, a treatment against WNT10B or WNT5B signaling pathways will only work on a subset of cancers because they activate different pathways." (PMID 39102216, 2024). "Therefore, we characterised WNT5B's relevance to cancer stem‐like cells, metastasis, and chemoresistance and evaluated its potential as a therapeutic target." (PMID 38689429, 2024). "WNT5B has been implicated in the CSC population in a few other cancers, even though its role in OS stem cells had not been explored." (PMID 38689429, 2024). "Also, other genes associated with metastasis and cancer progression were differentially regulated in tumour tissue, i.e., MMP13, WNT5B, and SOSTDC1." (PMID 39202425, 2024). "Only a few papers discuss the role of WNT5B in metastasis for other cancers." (PMID 38689429, 2024). "Moreover, the expression of the EMT mediators Notch1 and Wnt5B is increased, both of which are associated with breast EMT and cancer progression." (PMID 32699630, 2020). "Similarly, gene expression changes associated with breast EMT and cancer progression were detected, as the reduction of ERa and ERBB2 and the increase of NOTCH1 and WNT5B." (PMID 32699630, 2020). "Studies have shown that Wnt5b plays different roles in different types of cancers." (PMID 31130856, 2019). "Thus, RFP is useful for superficial tumor growth monitoring for cancer cells with Wnt5b-KD or treated with small molecules." (PMID 31462314, 2019). "Most likely, each WNT exhibits unique sensitivities and the response upon a particular tissue-derived cancer, which might be true for WNT5B in TNBC." (PMID 24564888, 2014). "WNT5B overexpression has been shown to enhance tumor invasiveness through the Wnt signaling pathway in some cancers; however, the underexpression of this gene in our cohort could reflect a distinct molecular mechanism or a specific feature of UTUC, potentially influencing tumor behavior." (PMID 40867248, 2025). "Our new anti-EpCAM sdAbs may inhibit cancer cell growth by decreasing WNT5B signaling." (PMID 40017594, 2025). "Therefore, we hypothesised that ROR1 is a viable and cancer‐specific target and began to target WNT5B through ROR1 inhibition." (PMID 38689429, 2024). "Therefore, we hypothesized that NOTCH pathway activation in ECs by JAG1 on cancer cells would induce WNT5B expression." (PMID 35673567, 2022). "WNT5B and TGFB1 expressions were increased in ECs through the interaction with JAG1 on cancer cells." (PMID 35673567, 2022). "FZD8, plasminogen activator, urokinase receptor, ITGA2, WNT2B, TIMP3, WNT5B, FGF5, heparanase, HBEGF and WNT3A were up-regulated in the proteoglycan pathways in cancer, whereas WNT10A, PIK3R3, IGF2 were down-regulated." (PMID 30482199, 2018). "Strikingly, cancer cell migration increased as a result of DNMT3A-3 L targeting, but decreased by TET1 targeting or overexpression of WNT5B complementary DNA (cDNA)." (PMID 29871649, 2018). "By focusing on a number of genes, selected because of their reported roles in human cancer (53BP1, CCND3, CLDN7, WNT5B, CAMKK1), we demonstrate the potential impact of this on the translational readout in each cellular context." (PMID 26589636, 2015). "Moreover, miR-5587-3P, miR-587, and miR-149-5P have been found to modulate WNT5B expression by binding to its 3' untranslated region (3'UTR) in, respectively, cancer, fat and chondrocytes cells 36-38." (PMID 40612684, 2025). "The role of WNT5B in cancers has not been extensively studied, but there are indications of WNT5B having tumor-promoting roles." (PMID 37971882, 2024).